EGF (epidermal growth factor)
Diseases named in the same sentence as EGF in open-access papers (continued):
Sharing a sentence is not in itself a finding about the gene and the disease.
tumor (continued). "Ligands for receptors present on tumor cells or tumor endothelium (e.g. EGF, FGF-2, VEGF) were coupled to PEG-coated virions to specifically target the vector to tumors." (PMID 21994711, 2010). "It is conceivable that by interacting with osteoblasts through paracrine EGF signalling, the tumour cells can ultimately promote osteoclastogenesis." (PMID 20010942, 2010). "This ligand of the EGF tyrosine kinase is commonly over expressed in cancers of human colon, stomach, breast, and pancreas, in which the level of Areg correlates with tumor progression and poor patient survival." (PMID 19529782, 2009). "The presence of MSC within the tumor also enhanced expression of growth factors such as EGF and HGF." (PMID 19352430, 2009). "We confirmed the presence of HGF, EGF and IL-6 within the tumor stimulated MSC population that we identify as TAF." (PMID 19352430, 2009). "Perhaps it is the tumor expression of IL-23, IL-6, epidermal growth factor or Janus kinase 2 or an undefined factor that ultimately regulates the expression of PBMC p-STAT-3 levels, but this was not determined in our current study." (PMID 19900287, 2009). "The HGF and EGF staining by IHC were present at concentrated amounts on the leading edge of tumor where a large portion of stroma is found in the admixed Skov-3/MSC tumors as compared to the Skov-3 only tumors." (PMID 19352430, 2009). "By linking EGF and IL-4, two well-known tumour-targeting ligands, to a truncated pseudomonas exotoxin A molecule, we created a novel recombinant agent that showed potent in vitro and in vivo activity." (PMID 19755995, 2009). "In particular tumor models, the addition of EGF serves to activate the ras →raf →MEK→ERK cascade as a collateral stimulus to TGF-βR-dependent signaling." (PMID 20204159, 2009). "Consistent with its critical role in cell proliferation and survival components of the EGF signalling networks are frequently constitutively activated within tumours." (PMID 19388902, 2009). "Costimulation of human cutaneous SCC (HaCaT II-4) cells with TGF-β1+EGF promotes a plastic transition typical of late-stage tumor progression." (PMID 20204159, 2009). "It has been shown that EGF stimulation produces a redistribution of α6β4 integrin from hemidesmosomes to the lamellipodia and filopodia of invasive tumor cells." (PMID 19470173, 2009). "Eleven patients having tumour EGFR expression by immunohistochemistry with low serum EGF and TGF-α levels showed a 100% RR compared to 37.0% in the remaining 27 patients (P<0.001)." (PMID 19127259, 2009). "Similar to wound healing, macrophages can secrete growth factors (e.g. epidermal growth factor (EGF)) during tumour progression that can alter the behaviour of the tumour cells possibly by providing a chemoattractive signal." (PMID 19077226, 2008). "Serum-starved SUM149 cells were stimulated with 5% FBS/growth media, EGF or the tumour promoter PMA." (PMID 19036157, 2008). "Induction of endothelial cell growth is accomplished by IL-8, Fms Related Tyrosine Kinase (Flt-3 Ligand), and PDGFs, while EGF and Transforming Growth Factors-β1, β2, and β3 (TGFs) are involved in tumor growth and proliferation." (PMID 18616824, 2008). "Despite considerable heterogeneity in activated STAT3 IHC staining as displayed from the images, an increase in staining is noticeable after EGF stimulation within the viable tumor area which is in agreement with Western blotting." (PMID 17326824, 2007). "More recent studies have added autocrine stimulatory factors such as EGF to the earlier models to more accurately reflect spatial characteristics of tumor tissue including the thickness of the proliferating rim in tumor spheroids." (PMID 19936081, 2007). "Tumor cell lines often express laminin-332 and the expression is enhanced by epidermal growth factor." (PMID 16483354, 2006).
tumor (continued). "In vitro studies indicated that the antiangiogenic effect was due to the ability of bexarotene to inhibit endothelial cell growth and decrease tumour cell-mediated endothelial cell invasion through reduction of VEGF and EGF secretion from tumour cells." (PMID 16495926, 2006). "We have previously demonstrated that the growth factor EGF induces HER2 protein expression in primary breast cultures derived from patient tumours, thus implicating an activated MAPK pathway in HER2 transcriptional regulation." (PMID 17060941, 2006). "In this study, growth factors, bFGF and EGF upregulated the protein expression of PEA3 in human primary tumour cell cultures." (PMID 17060941, 2006). "The EGFR autocrine signalling pathway is central to cancer progression, and overexpression of EGFR and/or its ligands, transforming growth factor (TGF)-α and EGF has been reported in many human tumours." (PMID 15928657, 2005). "Other agents with direct antitumour activity inhibit growth factors that play a key role in tumour cell proliferation and survival, the most prominent of these is epidermal growth factor (EGF)." (PMID 15928655, 2005). "Tumour staging is considered to be the best prognostic marker, but several other markers including the presence of members of the epidermal growth factor (EGF) family have been suggested." (PMID 15583696, 2004). "The adaptor protein PLC-γ1 was chosen as a target due to its pivotal role in the EGF-dependent migration and invasiveness of tumour cells mediated by EGFR and c-erbB-2 signalling." (PMID 14710234, 2004). "EGF treatment of tumour cell lines induces HIF-1α expression and constitutively active mutations of EGFR potentiate hypoxic induction of other targets of HIF-1α such as VEGF." (PMID 15365565, 2004). "Among the proto-oncogenes, the epidermal growth factor (EGF) family plays an important role in local tumour growth." (PMID 12966408, 2003). "EGF, acting through its receptor also stimulates the production of vascular endothelial growth factor by tumour cells, contributing further to the angiogenic response." (PMID 12402142, 2002). "Although EGF can have direct effects on tumour cells, it also promotes angiogenesis, predominantly through a mitogenic effect on endothelial cells." (PMID 12402142, 2002). "Of the malignant tumours, 70% (53/76) expressed EGF receptor mRNA, 31% (23/75) expressed EGF mRNA and 35% (26/75) expressed TGF-alpha mRNA." (PMID 8562334, 1996). "Results were correlated with tumour parameters (T-,N-stage, histology, grade, oestrogen and epidermal growth factor (EGF) receptors), and the impact on survival was assessed." (PMID 8932345, 1996). "One therapeutic strategy for overcoming EGF autocrine control of tumour growth is inhibition of EGFR protein tyrosine kinase (PTK)." (PMID 8956783, 1996). "Tumour samples had much higher TGF-alpha levels compared with EGF and TGF-alpha levels in malignant tissue were significantly higher than in benign bladder samples." (PMID 8605103, 1996). "Mitotic activity of these tumours detected by immunohistochemical staining for incorporated bromodeoxyuridine indicated a mitosis-stimulatory effect of endogenous and exogenous EGF on A431 tumours." (PMID 7547232, 1995). "The effect of epidermal growth factor (EGF) on the biological behaviour of human tumours in vivo is still controversial." (PMID 7547232, 1995). "Melatonin (aMT) appears to be a potentially important oncostatic substance that can block the mitogenic effects of tumour-promoting hormones and growth factors such as oestradiol and epidermal growth factor, in vitro." (PMID 8519656, 1995). "Forty-one human tumour cell lines were examined for the production of epidermal growth factor (EGF)/transforming growth factor (TGF)-alpha-like activity (EGF/TGF-alpha-LA), immunoreactive (IR-) EGF and IR-TGF-alpha." (PMID 2736210, 1989).
tumor (continued). "Notably, genes implicated in oncogenic signaling and tumor progression, including GNB4, EGF, MYB, IL6R, ANGPT4, and ITGB8, were consistently downregulated in both BxPC3 and SW1990 cells following PCDH1 silencing." (PMID 41602375, 2026). "The enhanced VEGF, EGF signaling pathway mainly occurs between tumor cells and endothelial cells." (PMID 41487509, 2025). "We observed that GBM tumor cells of U251 or GBM-b express TSLP when stimulated with EGF." (PMID 41516199, 2025). "Additionally, they revealed that this increased motility resulted from a positive feedback loop consisting of colony‐stimulating factor 1 (CSF1) released by tumor cells and epidermal growth factor (EGF) secreted by TAMs in a paracrine manner." (PMID 40257446, 2025). "Furthermore, macrophages promote invasion and metastasis by engaging tumor cells in an autocrine loop via EGF signaling." (PMID 41516258, 2025). "Additionally, pharmacological inhibition of USP21 with BAY-805 effectively reduced EGF-induced tumor spheroid formation, highlighting its therapeutic potential." (PMID 40629473, 2025). "Tumor-associated myeloid cells and microglia (TAMs) (key components of the GBM microenvironment) contribute to GBM progression by secreting cytokines and chemokines, such as PDGFB, EGF, SDF-1α, IL-6, and IL-8." (PMID 40867240, 2025). "Additionally, EGF creates conditions that mimic the tumor microenvironment, enhancing our understanding of HER2’s role in tumor progression." (PMID 40642068, 2025). "A similar experiment on co-localization of EGF-QDs with markers of the endocytic pathway in the control and under deacidification conditions on A549 tumor cells, which express a high number of EGFR, demonstrated the variability of endocytosis dynamics in tumor models (confocal images not provided)." (PMID 41155514, 2025). "Furthermore, in response to neuroblastic tumors cells, monocytes can differentiate into TAM, which can promote tumor cell invasion through a paracrine mechanism involving colony-stimulating factor 1 (CSF-1) and epidermal growth factor (EGF)." (PMID 40786507, 2025). "In neoplastic diseases, EGF‐induced macropinocytosis may support cancer cell proliferation and survival by enhancing nutrient uptake." (PMID 40266031, 2025). "Similarly to EGF, the tumor cell secretes an excess of VGEF, which interacts with the V and subsequently stimulates VGEFR." (PMID 41155569, 2025). "It has been established that elevated levels of EGF in the tumor microenvironment may be associated with the ability of tumor cells to metastasize; in cell culture of both HPV-positive and HPV-negative CC lines, EGCG effectively blocked the action of EGF." (PMID 39861342, 2025). "Furthermore, FABP5 regulates the expression of VEGF through PPARγ and enhances the expression of other angiogenic factors, including EGF and IL‐6, thereby promoting tumor angiogenesis." (PMID 40178066, 2025). "In contrast, EGF displayed a tumor type–specific methylation profile." (PMID 40692603, 2025). "Additionally, genipin decreases tumor cells’ resistance by lowering the expression of EGF, EGFR, PKB, and GSK-3β." (PMID 40656954, 2025). "In vivo, EGF released from KI-treated normal tissues together with KI-mediated unaltered EGFR expression in cancerous cells like SGC cells could drive tumor progression." (PMID 40508009, 2025). "Some tumor cells overexpress receptors of the epidermal growth factor (EGF)." (PMID 40807472, 2025). "Through STAT3 activation, CD206+ M2 TAMs sustain a pro-tumor milieu, releasing VEGF, TGF-β, EGF, urokinase-type plasminogen activator (uPA), and multiple matrix metalloproteinases (MMPs), thereby promoting tumor growth, immune suppression, angiogenesis, metastasis, and chemoresistance." (PMID 40948759, 2025). "Importantly, treatment with 10 μM PYCR1-IN-1 significantly reduced the size of EGFR- or TLR-induced tumor spheroids in H1299, H460, A549, H358 cells compared with cells treated with EGF or TLR agonists alone." (PMID 41254241, 2025).
tumor (continued). "N-glycosylation in the Golgi complex generates ligands for lectins, including the EGF receptor (EGFR) 63, suggesting that aberrant glycosylation may activate the EGF pathway in tumor cells." (PMID 40861802, 2025). "Additionally, platelets promote tumor growth and angiogenesis by releasing VEGF, PDGF, and EGF, supporting neovascularization and tumor microenvironment remodeling." (PMID 40647360, 2025). "By comprehensively evaluating the serological EGF levels in patients with CRC, we discovered that PDX tumors with low EGF levels exhibited a tumor inhibition value of approximately 40%, whereas those with high EGF levels exhibited a tumor inhibition value of less than 20% with OX40 agonists." (PMID 40026246, 2025). "By integrating gene expression, epigenetic, immune, and survival data, this analysis underscores the central roles of CCL18 and EGF within the tumor ecosystem and highlights the value of network-based approaches in uncovering novel regulatory axes in cancer progression." (PMID 40692603, 2025). "Notably, NOX4-driven M2-polarized macrophages exhibit elevated JNK activity and secrete heparin-binding EGF-like growth factor (Hb-EGF), thereby stimulating NSCLC proliferation, identifying TAMs as a key EGF source in the tumor microenvironment." (PMID 41058699, 2025). "Considering the crucial role of EGF signaling in OX40 protumor effects in tumor ECs, we hypothesized that EGF signaling inhibitors would disrupt the adverse protumor effects of OX40 in ECs." (PMID 40026246, 2025). "Furthermore, epidermal growth factor (EGF), an important protein in stimulating tumor growth, was used to promote the growth of SKOV3 tumor spheroids." (PMID 40093794, 2025). "Moreover, a recent study indicated that CCL2 induces macrophages to express epidermal growth factor (EGF), enhancing tumor proliferation and metastasis through the activation of the EGFR receptor." (PMID 40134607, 2025). "Besides, many past studies on tumor cell metastasis in microfluidic chips focused on biochemical signal-induced migration, such as the chemotactic migration of tumor cells induced by epidermal growth factor and CXCL12 chemokine." (PMID 40510151, 2025). "Derivation of a gene expression signature for autonomy revealed that growth signaling autonomy is uniquely induced in circulating tumor cells (CTCs), the harshest phase in the life of tumor cells when it is deprived of biologically available epidermal growth factor (EGF)." (PMID 38312224, 2024). "By paracrine signaling loops involving CSF-1 from the tumor and EGF from macrophages, TAMs may encourage tumor cell invasion." (PMID 38326735, 2024). "Moreover, in vivo experiments with HisSaporin-A2-EGF did not only reveal superiority over HisSaporin-EGF in terms of tumor growth inhibition." (PMID 38685061, 2024). "Additionally, PLSCR1 is thought to be involved in tumour proliferation because its overexpression has been observed as part of EGF stimulation pathways." (PMID 38391955, 2024). "Moreover, tumor endothelial cells show different responsiveness to epidermal growth factor (EGF), adrenomedullin, and VEGF compared with normal endothelial cells." (PMID 38576482, 2024). "In agreement, senescent fibroblasts express various proliferation-inducing factors (e.g. HGF, CXCL12 and EGF), can induce treatment resistance via inducing tumor cell EMT, or metabolically support tumor cell progression and metastasis by upregulating glycolysis and ketone production." (PMID 39696386, 2024). "Macrophages within the TME release proteolytic enzymes that breakdown the extracellular matrix and trigger a positive feedback loop consisting of tumor cell-produced CSF-1 and TAM-produced EGF promoting chemotactic migration of tumor cells toward blood vessels." (PMID 38533720, 2024). "Similarly, samples in cluster C2 displayed higher expression in multiple tumor-associated physiological pathways including AKT, EGF, HER2, MAPK, MET, mTOR, PTEN, RAS, WNT and NOTCH signal pathway." (PMID 38434969, 2024).
tumor (continued). "Once TAMs are recruited and located at the perivascular or at the invasive edge of the tumor, they secrete promigratory factors such as epidermal growth factor (EGF), which facilitates the proteolytic remodeling of the extracellular matrix (ECM) and accelerates tumor motility." (PMID 38672714, 2024). "TAMs are key cellular sources of EGF secretion in tumor tissues." (PMID 39513610, 2024). "Interestingly, addition of EGF instead of AREG would have reduced intra-tumor heterogeneity and generated worse JSD scores." (PMID 37776423, 2024). "Once the tumour is established, TAMs are "re-educated" into the M2 phenotype, which supports tumour growth and promotes tumour progression through the production of tumour growth factors (e.g. EGF, FGF, TGFb, PDGF) and pro-angiogenic molecules (e.g. TGFb, PDGF)." (PMID 39060648, 2024). "Secondly, MSCs may promote the proliferation of tumor cells and thereby increase their tolerance to treatment by secreting growth factors such as EGF and FGF-β." (PMID 39697553, 2024). "Aberrant glycosylation in SEMA7A could be induced by cytokines in the tumor microenvironment, such as EGF and TGF-β1, through distinct molecular pathways." (PMID 38548747, 2024). "EGF has previously been shown to support growth and tumor spread." (PMID 38393158, 2024). "While we did not look at MAPK in our analysis, we observed that there was an increase in proliferative markers EGFR and PCNA by PCR and EGF in serum in patients who received sorafenib/RT, which may enhance the proliferation of tumor cells." (PMID 38542325, 2024). "To mimic such tumor heterogeneity, we have mixed the clones overexpressing or silenced for CD at different ratios and tested which one would take advantage to grow over the other in the absence or in the presence of EGF stimulation." (PMID 38611021, 2024). "We considered all identified cell types in ECEC as source cells for the EGF signaling pathway, and the results indicated that all subtypes of MCs could target tumor cells with released EGF." (PMID 39430754, 2024). "Moreover, EGF secreted by TAMs, causes EGFR activation in tumor cells, which upregulated the VEGF/VEGFR signaling pathway in the surrounding, thus stimulating the proliferation and migration of cancer cells." (PMID 39003350, 2024). "Interestingly, our results showed that EGF was upregulated, while previous studies showed that EGF upregulation promoted tumor cell proliferation or invasion, and the knockdown of this gene inhibited tumor cell proliferation." (PMID 39346787, 2024). "Moreover, we observed a 20-fold induced expression of LIM homeobox domain 9, i.e. a putative tumor suppressor which was highly responsive to tobacco smoke exposure and determined 3-fold induced expression of epidermal growth factor to stimulate EGFR signaling." (PMID 37932771, 2023). "After immortalization, the cells did not acquire characteristics of neoplastic transformation, as noted by the lack of colony formation in soft agar, which could be restored after exposure to tumor promoters such as EGF." (PMID 37635218, 2023). "In addition, TAM and M2 Macrophages can promote chronic inflammation, angiogenesis, and tumor growth by secreting various cytokines, growth factors (e.g., EGF, VEGF, PDGF, FGF and TGFβ), matrix metalloproteinases (MMPs), M-CSF, etc.." (PMID 36859111, 2023). "Thus, for the first time we identified that stabilin-1 acts as a scavenger receptor for internalization and endocytic trafficking of EGF, an essential regulator of tumor growth." (PMID 36960065, 2023). "EGF has been used as a tumor promoter in many experimental systems, including UROtsa cells." (PMID 37635218, 2023). "Furthermore, the relationship between LAD1 expression and K-Ras and EGF signaling activation, tumor cell proliferation, migration, and colony formation was studied by gene knockout/knockout methods." (PMID 36770773, 2023).